IL27 (interleukin 27)
Diseases named in the same sentence as IL27 in open-access papers (continued):
Sharing a sentence is not in itself a finding about the gene and the disease.
injury (1 paper, 2021). Damage inflicted on the body as the direct or indirect result of an external force, with or without disruption of structural continuity. "Previous research indicated that elevated IL-27 levels were positively correlated with Th17 cells in patients with liver injury." (PMID 34744512, 2021). "Most recently, one study reported that in liver injury patients, serum IL-27 was increased and positively related to Th17 cells, which also supports our findings." (PMID 34744512, 2021).
latent infection (1 paper, 2018). "Together, these data show that IL-27 regulates the number and effector functions of MCMV-specific CD4 T cells and could be targeted to enhance control of persistent/latent infection." (PMID 30044874, 2018).
medulloblastoma (1 paper, 2023). A malignant, invasive embryonal neoplasm arising from the cerebellum. "While pathways involved in cell cycle, and DNA repair were up-regulated in medulloblastoma, NFΚB pathway, RELA pathway, Interleukin-2 (IL2), Interleukin-27(IL27) signaling pathways were down-regulated in medulloblastoma compared to healthy cerebellum samples from GTEx." (PMID 36918656, 2023).
metastatic melanoma (1 paper, 2013). A melanoma that has spread from its primary site to another anatomic site. "Indeed, when positivity for IL-27 was observed in tumor cells in the primary cutaneous tumor (10/15 cases), it was maintained in the metastatic melanoma." (PMID 24130734, 2013). "Interestingly, comparison of IL-27 staining in primary and metastatic melanoma from the same patient showed that expression of EBI3 and p28 by tumor cells was not downregulated upon tumor progression." (PMID 24130734, 2013). "We also analyzed cases of metastatic melanoma (n = 19) for IL-27 expression." (PMID 24130734, 2013). "Analysis of IL-27 expression in primary cutaneous and metastatic melanoma from single patients." (PMID 24130734, 2013).
mononucleosis (1 paper, 2025). "Beata found that the serum level of IL-27 was significantly higher in children with mononucleosis than in healthy participants and positively correlated with ALT, AST, LDH activity, and WBC count." (PMID 40837353, 2025).
Myocardial fibrosis (1 paper, 2025). "Numerous studies have confirmed that IL-27 not only promotes myocardial fibrosis by acting independently, but also indirectly promotes the process of myocardial fibrosis by activating related signaling pathways." (PMID 40881586, 2025). "IL-27 regulates the function of fibroblasts and promotes the differentiation of fibroblasts into myofibroblasts, which directly promotes myocardial fibrosis." (PMID 40881586, 2025). "Meanwhile, IL-27 promotes the activation of Janus kinases (JAKs)/STAT signaling pathway in myocardial fibroblasts, which is involved in the process of myocardial fibrosis." (PMID 40881586, 2025).
Nephropathy (1 paper, 2025). A nonspecific term referring to disease or damage of the kidneys. "Less-characterized interleukins such as IL-3, IL-5, IL-9, and IL-27 demonstrate dual or context-dependent roles, particularly in shaping immune tolerance and tissue-specific complications such as nephropathy and neuropathy." (PMID 40804870, 2025).
Pain (1 paper, 2019). An unpleasant sensory and emotional experience associated with actual or potential tissue damage, or described in terms of such damage. "Next, we determined whether IL-27 plays a role in the development of chronic neuropathic pain induced by SNI." (PMID 32047492, 2019).
Parkinson disease (1 paper, 2022). A progressive degenerative disorder of the central nervous system characterized by loss of dopamine producing neurons in the substantia nigra and the presence of Lewy bodies in the substantia nigra and locus coeruleus. "IL-27 is induced by other pro-survival molecules and potentially contributes to their cytoprotective functions, including GM-CSF-induced survival of dopaminergic neurons in a mouse Parkinson’s disease model, and matrine-dependent neuroprotection in the EAE mouse model." (PMID 36064575, 2022).
peripheral arterial disease (1 paper, 2025). A disorder of the arteries supplying the upper and lower extremity and the visceral organs. "This prospective cohort study evaluated association of circulating IL-27 levels in peripheral artery disease patients undergoing elective endovascular revascularization, with major adverse cardiovascular events (MACE) and major adverse limb events (MALE) over a median follow-up of 311 days." (PMID 41302192, 2025). "Our study is the first to provide evidence on the prognostic role of IL-27 in peripheral artery disease." (PMID 41302192, 2025). "Ours is the first study to address the long-term prognostic impact of circulating IL-27 levels in patients with peripheral artery disease." (PMID 41302192, 2025). "Circulating plasma levels of IL-27 represent a prognostic predictor in patients with peripheral artery disease." (PMID 41302192, 2025). "Thus, the aim of our study was to evaluate prognostic role of IL-27 in patients with peripheral arterial disease undergoing elective endovascular revascularization." (PMID 41302192, 2025). "We hypothesized that elevated circulating IL-27 levels would be associated with increased risk of major adverse cardiovascular events (MACE) and major adverse limb events (MALE) in patients with peripheral artery disease." (PMID 41302192, 2025). "Thirdly, our observational study provides evidence of association, but not necessarily causation, between IL-27 and clinically relevant outcomes in patients with peripheral artery disease." (PMID 41302192, 2025). "Conversely, in patients with peripheral artery disease, the role of IL-27 has not been studied yet." (PMID 41302192, 2025).
peripheral nerve injury (1 paper, 2019). Injury to a peripheral nerve. "Altogether these results indicate that the antinociceptive effect of exogenous and endogenous IL-27 upon neuropathic pain caused by peripheral nerve injury depends on the induction of IL-10 expression on myeloid cells in the DRGs." (PMID 32047492, 2019). "In conclusion, they indicate that immunotherapies based on IL-27 could emerge as possible therapeutic approaches for the prevention of neuropathic pain development after peripheral nerve injury." (PMID 32047492, 2019). "Finally, they indicate that immunotherapies based on IL-27 could emerge as possible therapeutic approaches for the prevention of neuropathic pain development after peripheral nerve injury." (PMID 32047492, 2019). "However, no significant changes in the expression of macrophage/glial cell activation markers and their derived pro-nociceptive cytokines (TNF and IL-1β) were detected after peripheral nerve injury in the DRGs and spinal cord from IL-27 null mice compared to WT mice." (PMID 32047492, 2019).
psoriatic arthritis (1 paper, 2026). Joint inflammation associated with psoriasis. "Ninety pediatric participants (JIA, CD, psoriatic arthritis, healthy controls) underwent serum cytokine profiling (IL-1α, IL-1β, IL-36α, IL-37, IL-6, IL-18, IL-27, IL-31) at baseline and 12 months." (PMID 42196228, 2026).
rectal cancer (1 paper, 2021). A primary or metastatic malignant neoplasm that affects the rectum. "While in the rectal cancer TME, CD80 levels on DCs correlated positively with Flt-1 and inversely with IL-27." (PMID 33540635, 2021).
renal hypertension (1 paper, 2024). Hypertension caused by the kidney's hormonal response to narrowing or occlusion of the renal arteries. "Loss of IL-27 signaling, as observed in IL-27Rα-deficient models, exacerbates tubulointerstitial fibrosis and enhances Th17-mediated inflammatory responses, highlighting its potential inhibitory role in renal hypertension." (PMID 39906735, 2024). "Mechanistically, IL-27 appears to inhibit renal fibrosis, a key factor in the development of renal hypertension." (PMID 39906735, 2024).
retinal (1 paper, 2024). "Serum IL-27 levels also did not significantly correlate with retinal lesion size in OT (p=0.556)." (PMID 38314317, 2024).
retinal degeneration (1 paper, 2022). Degeneration of the retina. "We demonstrated using histological, molecular, functional and behavioral assays that a single intravitreal injection of the cytokine IL-27 induced significant photoreceptor protection and suppressed inflammation in a mouse model of retinal degeneration." (PMID 36064575, 2022). "This study is the first to identify survival and anti-inflammatory effects of IL-27 during retinal degeneration and adds new information about regulatory signals that control inflammation in the retina." (PMID 36064575, 2022). "Our findings demonstrate that IL-27 increased photoreceptor survival, stabilized visual acuity and rescued rod and cone functional responses in the rd10 retinal degeneration model." (PMID 36064575, 2022). "The purpose of the current study was to characterize the effect of exogenous IL-27 under conditions of elevated neurotoxic inflammation during retinal degeneration." (PMID 36064575, 2022). "We demonstrate that recombinant IL-27 decreased photoreceptor death, increased retinal function and reduced inflammation in the rd10 mouse model of retinal degeneration." (PMID 36064575, 2022). "Our results identify for the first time anti-inflammatory and neuroprotective activities of IL-27 in a genetic model of retinal degeneration." (PMID 36064575, 2022). "Therefore, the ERG results demonstrate that IL-27 increased retinal function in a mouse model of severe retinal degeneration." (PMID 36064575, 2022). "IL-27 is neuroprotective in the brain, but its function during retinal degeneration has not been investigated." (PMID 36064575, 2022). "However, whether IL-27 regulates inflammation and photoreceptor survival in a genetic model of retinal degeneration, which does not show T cell involvement, has not been investigated." (PMID 36064575, 2022).
retinal ischemia (1 paper, 2021). A ischemic disease that involves the retina. "Neither IL27 nor IL6 were associated with retinal ischemia, unlike that seen in ONH ischemia." (PMID 34207618, 2021).
rheumatic disorder (1 paper, 2024). Inflammatory and degenerative diseases of connective tissue structures, such as arthritis. "We found that 11 proteins had a significant association with rheumatic disorders with Bonferroni correction (eTable 13 in Supplement 1), namely, interleukin-27, ICAM5, LMAN2L with JIA; TIMP4 with SSc; and 6 proteins with RA, and 4 proteins with SLE." (PMID 39729320, 2024).
sarcoma (1 paper, 2025). A usually aggressive malignant neoplasm of the soft tissue or bone. "It includes information on cytokines that have been poorly studied in sarcoma peripheral blood samples, such as IL-24, IL-27, CCL21, CXCL5, and CXCL14." (PMID 41008853, 2025). "The remaining analytes, IL-8, IL-10, IL-12 P40, IL-24, IL-27, and CXCL10 were found in similar plasma concentrations in both patients with sarcoma and healthy subjects." (PMID 41008853, 2025).
Sciatica (1 paper, 2021). Pain in the lower back and hip radiating in the distribution of the sciatic nerve. "The roles of SLC8A1, RBM20, GPER1, IL27, SOCS1, and GRTP1-AS1 in sciatica or in relieving sciatica are currently unknown." (PMID 33573686, 2021).
skin cancer (1 paper, 2016). "The cytokine IL27 has pleiotropic functions, including pro- and anti-inflammatory properties in inflammatory and infectious diseases, but the function of IL27 during initiation of skin cancer is obscure." (PMID 27738312, 2016).
skin tumor (1 paper, 2016). "Collectively, these data demonstrate that IL27 signaling through CD11b-positive cells are crucial for IL27-mediated promotion of angiogenesis, and skin tumor formation." (PMID 27738312, 2016). "Two step skin carcinogenesis model and K15-KRASG12D mouse model were used to understand the role of IL27 in skin tumors." (PMID 27738312, 2016). "Indeed, IL27-treated mice lacking CD11b−/− cells are ~4 times less likely to develop skin tumors when compared to wildtype mice." (PMID 27738312, 2016).
squamous cell carcinoma (1 paper, 2015). A carcinoma arising from squamous epithelial cells. "IL-27's effects were tested on Adenocarcinoma (AC) and Squamous Cell Carcinoma (SCC) cell lines and xenograft models." (PMID 25638163, 2015).
staphylococcus aureus infection (1 paper, 2020). An infectious process in which the bacteria Staphylococcus aureus is present. "IL‐27 also strongly stimulated CD4+T cell proliferation and Th1 cytokine production by up‐regulating the antigen‐processing capability of DC in the Staphylococcus aureus infection." (PMID 32761753, 2020).
status epilepticus (1 paper, 2021). Status epilepticus is defined as a continuous seizure lasting more than 30 min, or two or more seizures without full recovery of consciousness between any of them. "An unexpected finding in the present study was that knock-out of the P2X7R was associated with higher release of cytokines post-status epilepticus, including both pro- and anti-inflammatory cytokines (e.g., IL-10, IL-12p70, IL-27/30, IL-4, KC/GRO MIP-1α, MIP-2, TNF-α)." (PMID 34572093, 2021).
steatosis (1 paper, 2022). Increased lipid within the cytoplasm of cells.
synovitis (1 paper, 2016). Inflammation of a synovial membrane. "While patients having a high density of TLS displayed high synovial levels of IL-17 and IL-21, high levels of IL-27 were observed in patients devoid of any TLS, and IL-27 expression was inversely correlated with CD3+ and CD20+ infiltrates and with synovitis." (PMID 27752258, 2016).
syphilis (1 paper, 2019). A contagious bacterial infection caused by the spirochete Treponema pallidum. "Low Leptin and low IL27 were associated with incident syphilis whereas high Leptin and high IL27 were associated with treated infection (p-value: 0.009; OR, 16.5; 95% CI 2.25, 121.23)." (PMID 31186010, 2019).
Thrombocytopenia (1 paper, 2017). A reduction in the number of circulating thrombocytes. "In a recent study, thrombocytopenia was associated to elevated levels of IL-27, IL-10 and IL-6 cytokines." (PMID 28231825, 2017).
urolithiasis (1 paper, 2023). Stone(s) within the urinary tract. "However, there was no causal association between other common risk factors (PTH, CRP, IL6, IL18, IL27, IL8, IL16, IL1Ra, coffee consumption, age of smoking initiation, smoking initiation, and cigarettes smoked per day) and urolithiasis in the meta-analysis." (PMID 37624788, 2023).
viral pneumonia (1 paper, 2025). Inflammation of the lung parenchyma that is caused by a viral infection. "Viral pneumonia has been predicted by IL6, IL27, and CRP, with distinct cytokine expression profiles differentiating viral from bacterial community-acquired pneumonia." (PMID 41373577, 2025).
vitiligo (1 paper, 2020). Generalized well circumscribed patches of leukoderma that are generally distributed over symmetric body locations and is due to autoimmune destruction of melanocytes. "Results showed decreased concentration of IL-27 in vitiligo patients as compared with healthy subjects (p = 0.026)." (PMID 32616337, 2020). "Consistent with previous studies in SLE and BD patients, the present study showed that the concentrations of IL-27 serum levels were reduced in vitiligo patients, which can be justified through some probable mechanisms." (PMID 32616337, 2020). "The serum concentrations of IL-27 in 79 patients with generalized (72 cases) or localized (seven cases) vitiligo were observed using the ELISA technique." (PMID 32616337, 2020). "The results showed that there was a significant difference in serum concentrations of IL-27 between vitiligo patients (5267.8 ± 399 pg/mL) and healthy subjects (7097.7 ± 1502 pg/mL) (p = 0.0262)." (PMID 32616337, 2020). "The reduction in the serum levels of IL-27 in vitiligo patients compared to normal subjects suggested the possible anti-inflammatory role of this cytokine in vitiligo." (PMID 32616337, 2020). "The objective of this study was to determine the serum concentration of IL-27 in vitiligo patients and compare it with normal individuals." (PMID 32616337, 2020). "The serum concentration of IL-27 in 79 vitiligo patients was evaluated in comparison to 45 healthy controls using ELISA assay." (PMID 32616337, 2020). "Further studies with more patients of all types of vitiligo are needed to reveal the possible alterations in the concentration of IL-27 in those patients and their correlation with disease characteristics, including severity and the extension of the affected skin area." (PMID 32616337, 2020). "The present examination intended to evaluate the serum levels of IL-27 in vitiligo patients." (PMID 32616337, 2020). "The correlations between serum concentrations of IL-27 with gender, the severity of the disease, two types of (localized/generalized) vitiligo, segmental/nonsegmental forms of the disease, and response to treatment in patients with vitiligo were examined." (PMID 32616337, 2020). "Thus, IL-27 may be considered as a new target for the manipulation of the immune system in vitiligo patients." (PMID 32616337, 2020). "Cytokines have remarkable roles in the pathogenesis of vitiligo, such as IL-1, IL-6, and TNF-α; interleukin 27 (IL-27) is a new member of the IL-6/IL-12 family, mainly released by activated antigen-presenting cells." (PMID 32616337, 2020). "The concentrations of IL-27 in vitiligo patients have not yet been investigated." (PMID 32616337, 2020).
vivax malaria (1 paper, 2017). "Thus, the IL-27 role in vivax malaria needs further investigation." (PMID 28118834, 2017).